IER5L (immediate early response 5 like)
Synonyms: bA247A12.2
Tractability: PROTAC: ubiquitination databases record sites on it.
Gene: Protein-coding gene on chromosome 9 (129,175,552 to 129,178,261, reverse strand). Ensembl gene ENSG00000188483.
Subcellular location (Human Protein Atlas): Nucleoplasm
Genetic constraint (gnomAD): Loss-of-function variants: 6 observed, 13.95 expected, observed/expected ratio (o/e) 0.43, 90% interval 0.23 to 0.85. The synonymous counts are far from expectation, so gnomAD's model fits this gene poorly and the ratio says little. Missense variants: 607 observed, 415.06 expected, observed/expected ratio (o/e) 1.46, 90% interval 1.37 to 1.56. Synonymous variants: 349 observed, 216.65 expected, observed/expected ratio (o/e) 1.61, 90% interval 1.48 to 1.76.
Homologues: Orthologues: chimpanzee IER5L (99% identical), macaque IER5L (99% identical), dog IER5L (97% identical), pig IER5L (96% identical), rat Ier5l (95% identical), mouse Ier5l (94% identical), chimpanzee IER5L (92% identical), guinea pig IER5L (82% identical), tropical clawed frog ier5l (45% identical), zebrafish ier5l (43% identical). Paralogues in human: IER5 (21% identical), IER2 (14% identical).
Diseases named in the same sentence as IER5L in open-access papers:
IER5L is named in the same sentence as 15 diseases in open-access papers, as found by Europe PMC text mining. Sharing a sentence is not in itself a finding about the gene and the disease. The quoted sentences say what the papers report.
colon cancer (2 papers, 2010 to 2022). "The clinical relevance of CSTL1, FJX1, IER5L, and KLHL35 in 521 colon cancer cases was assessed, showing the expression level of CSTL1 mRNA was higher than that in normal tissues, and the expression levels of PD, SD, PR, and CR were higher than those in normal tissues." (PMID 35928453, 2022). "The upreguation of TAGLN and downregulation of SOX9, IRS1, P15, AREG, IER5L, KRT8 in RKO, SW620 and CW2 colon cancer cells indicated these genes may be the target molecules for the biological behaviour of IGFBP-rP1 in colon cancer." (PMID 20977730, 2010). "We found that IGFBP-rP1 could upreguate TAGLN, downregulate SOX9, IRS1, P15, AREG, IER5L, KRT8 in these colon cancer cells, indicating that these genes may be the important IGFBP-rP1 responsible genes in colon cancer." (PMID 20977730, 2010).
prostate carcinoma (2 papers, 2024 to 2025). A carcinoma that arises from epithelial cells of the prostate gland. "Further, IER5L depletion has been shown to reduce the growth, migration, and invasiveness of prostate cancer cells, indicating its importance for prostate cancer progression." (PMID 40002205, 2025). "Here, we show that the less studied member of this family, Immediate Early Response 5 like (IER5L), is upregulated in aggressive prostate cancer." (PMID 39025841, 2024). "In sum, we report the alteration of IER5L in prostate cancer and beyond and provide biological and molecular evidence of its contribution to tumor aggressiveness." (PMID 39025841, 2024). "IER5L silencing compromises tumor growth and decreases the capability of prostate cancer cells to form colonies in foci-formation assays as well as the anchorage-independent growth, while the population doubling rate in 2D unchallenged conditions remains unperturbed." (PMID 39025841, 2024). "In addition to IER5, IER5L and IER2—two homologues of IER5 with structural similarity —are also highly expressed and promote tumor progression, metastasis, and invasion in various cancers including prostate cancer, non-small cell lung cancer, melanoma, and colorectal cancer." (PMID 40002205, 2025).
dyslexia (1 paper, 2025). A learning disorder characterized by an impairment in processing written words. "The most significantly associated independent SNPs; rs13082684 (PPP2R3A), rs2426117 (CSE1L) and rs9696811 (located between PTPA and IER5L), were consistent with loci reported in the univariate dyslexia GWAS." (PMID 40825760, 2025).
gastric cancer (1 paper, 2025). A primary or metastatic malignant neoplasm involving the stomach. "IER5 and its family members IER5L and IER2 have been reported to be overexpressed in many cancers including ovarian, hepatic, lung, and gastric cancers." (PMID 40002205, 2025).
metastatic disease (1 paper, 2024). "Interestingly, the upregulation of IER5L expression exhibits a robust association with metastatic disease in prostate and is recapitulated in other cancer types." (PMID 39025841, 2024).
non-small cell lung carcinoma (1 paper, 2025). A group of at least three distinct histological types of lung cancer, including non-small cell squamous cell carcinoma, adenocarcinoma, and large cell carcinoma. "IER5L has been shown to be a prognostic marker for non-small cell lung cancer, with higher IER5L expression seen in patients with relapse versus no relapse." (PMID 40002205, 2025).
ovarian carcinoma (1 paper, 2025). A malignant neoplasm originating from the surface ovarian epithelium. "Further, since other IER5 family genes (IER2 and IER5L) have also been reported to regulate HSF1 activity, this family of genes may collectively be involved in the progression of ovarian cancer via the HSF1 pathway." (PMID 40002205, 2025). "Furthermore, analysis of data from an ovarian cancer mouse model seeded by OSE or FTE showed that higher expression of Ier5 is observed in ovarian cancer cells of OSE origin, whereas higher expression of Ier5l and Ier2 is observed in those derived from FTE." (PMID 40002205, 2025). "We found that Ier5 expression is elevated in ovarian cancer derived from OSE but not FTE, whereas both Ier5l and Ier2 were upregulated in those from FTE but not OSE." (PMID 40002205, 2025).
retinal degeneration (1 paper, 2021). Degeneration of the retina. "In the group of slow adapters, we identified several downregulated genes that are involved in the development and/or progression of retinal degeneration (Cebpb, Egr4, and Ier5l) or apoptosis (Nrtn, Ccdc85b, Junb and Jund)." (PMID 34404875, 2021).
tumor (4 papers, 2022 to 2025). "Mechanistically, our results indicate that the tumor suppressive phenotype elicited upon IER5L targeting is associated to changes in the transcriptional program of proliferation and monomeric G protein regulators such as RCC2 and ARHGEF1." (PMID 39025841, 2024). "To analyze the association of IER family members (IER2, IER5 and IER5L) with tumor pathogenesis and progression, we interrogated public transcriptomics datasets containing gene expression data from different tumor types using Cancertool." (PMID 39025841, 2024). "In this study, we exploit bioinformatics analysis of public transcriptomics datasets to find a consistent and unique association of IER5L expression among the IER family genes with tumor pathogenesis, progression and metastasis." (PMID 39025841, 2024). "Of note, the silencing efficacy of the two human IER5L-targetting shRNAs was associated with the proportional tumor suppressive phenotype." (PMID 39025841, 2024). "Taking advantage of cellular systems, we show that IER5L sustains the proliferation under stress, migration and invasion capacity of PCa cells, and that its depletion compromises tumor growth and dissemination in vivo using zebrafish and murine models." (PMID 39025841, 2024). "Unlike IER2 and IER5, the role of IER5L has been poorly studied and thus, we lack basic understanding of the possible contribution of IER5L to tumor progression and metastasis." (PMID 39025841, 2024). "IER5L-silenced cells showed a lower luciferase signal throughout the experiment, which correlated with a reduced primary tumor weight at the experimental endpoint." (PMID 39025841, 2024). "In this study, we identify IER5L as a gene that is upregulated in different cancer types, including PCa, and that IER5L upregulation contributes to the maintenance of metastatic properties of PCa tumor cells in vitro and in vivo." (PMID 39025841, 2024). "To further explore whether the increase in IER5L levels was a common feature of different tumor types, we took advantage of TIMER web interface, which allowed us to explore the cancer-associated alterations in the TCGA cohorts." (PMID 39025841, 2024). "Some CSC marker genes showed extremely disparate expression levels between normal and tumor samples, such as PLCG2, DDX11, IER5L, LENG8, HAGHL and CPNE7." (PMID 37377935, 2023). "The Mann-Whitney U test (Wilcoxon rank-sum test) for unpaired samples showed the expression of CSTL1, FJX1, IER5L, and KLHL35 in tumor tissue was higher than that in normal tissue." (PMID 35928453, 2022). "By contrast, IER5L was consistently upregulated in colorectal (2/2 datasets), lung (1/1 datasets) and prostate (2/4 datasets) tumor specimens when compared to non-cancerous tissue, consistent with recent reports." (PMID 39025841, 2024).
cancer (3 papers, 2022 to 2025). A tumor composed of atypical neoplastic, often pleomorphic cells that invade other tissues. "Our bioinformatics analysis revealed an association of IER5L upregulation to cancer progression." (PMID 39025841, 2024). "Our results show that IER5L is a prognostic gene whose expression is upregulated across different cancer types, with a remarkable overexpression in metastatic PCa." (PMID 39025841, 2024). "The results obtained in this study reveal that IER5L expression is altered in PCa and other cancers, and that its levels contribute to cancer-related biological processes." (PMID 39025841, 2024). "The promoter methylation levels of FJX1, KLHL35, and IER5L in primary malignant tumors were higher than those in normal tissues." (PMID 35928453, 2022). "Further studies around the mechanism of regulation and function of IER5L could provide relevant information to deconstruct the molecular bases of cancer pathogenesis and progression." (PMID 39025841, 2024). "IER5L levels consistently increased across cancer types (with a similar non-significant trend in PCa), while IER2 expression was largely reduced, and IER5 exhibited inconsistent alterations." (PMID 39025841, 2024). "IER5L is a member of the IER family that shares homology at its N-terminal domain with IER2 and IER5, which reportedly contribute to different aspects of cancer biology." (PMID 39025841, 2024). "Unlike IER2 and IER5, the role of IER5L in cancer aggressiveness has been poorly studied." (PMID 39025841, 2024).
IER5L also shares sentences with these, for which no sentence is quoted: colorectal cancer (1 paper); infection (1); latent infection (1); melanoma (1); metastatic cancers (1).